ENSG00000252329
Synonyms: LOC124900312
Gene: Small Cajal body-specific RNA gene on chromosome 11 (12,904,817 to 12,904,988, reverse strand). Ensembl gene ENSG00000252329.
Gene Ontology:
Biological process: RNA processing
Cellular component: nucleolus